LYZ (lysozyme)
Diseases named in the same sentence as LYZ in open-access papers (continued):
Sharing a sentence is not in itself a finding about the gene and the disease.
colorectal cancer (8 papers, 2022 to 2025). A primary or metastatic malignant neoplasm that affects the colon or rectum. "The loss of LYZ+ cells by Dkk2 knockout rescued mice from the liver metastasis of colorectal cancer induced by cancer organoid transplantation." (PMID 38659853, 2024). "LYZ is associated with incidence of colorectal cancer and lymph node metastasis." (PMID 36505781, 2022). "We discovered that 428 DEGs had a causal association with colorectal cancer through eQTL, of which 38 genes met the FDR statistical standards, and four of these genes (CTSF, PCSK7, LYZ, LMAN2L) also had causal associations through pQTL." (PMID 40381082, 2025). "Further comparison of gene expression differences between right-sided and left-sided colorectal cancer tumor cells revealed that genes such as MTRNR2L8, CHRNA7, TFF1, and LYZ were more highly expressed in right-sided colorectal cancer." (PMID 41174721, 2025). "In sum, our findings suggest that a Wnt ligand, DKK2 is an upstream regulator of SOX9 expression for enhanced stem cell activity via the formation of LYZ+ cells with Paneth cell characteristics in colorectal cancers." (PMID 38659853, 2024). "Characterization of DKK2-induced LYZ+ cancer cells will provide better understanding of the biology of cancer stem cell niches, particularly in liver metastases of colorectal cancer." (PMID 38659853, 2024). "Collectively, DKK2 is required for the generation of LYZ+ cells to form the cancer stem cell niche, a prerequisite for the outgrowth of metastasized colorectal cancer cells." (PMID 38659853, 2024). "This delineates the distribution of LYZ+ cancer cells with Paneth cell characteristics in different stages of colorectal cancer progression." (PMID 38659853, 2024). "This extends our knowledge of colorectal cancer progression that DKK2 is required for the generation of LYZ+ cells forming cancer stem cell niches." (PMID 38659853, 2024). "Further research is also needed to investigate if NOD2 expression in phagocytes may favor colorectal cancer through limiting lysozyme-dependent anti-cancer properties such as direct activation of immune effectors and immunosuppressive antioxidant properties." (PMID 37876927, 2023). "By integrating single-cell data, transcriptomic data, proteomic data and GWAS data for MR analysis, we identified CTSF, PCSK7, LYZ, LMAN2L as potential targets for colorectal cancer." (PMID 40381082, 2025). "This study identified CTSF, PCSK7, LYZ, and LMAN2L as critical regulatory genes in colorectal cancer, demonstrating their multifaceted clinical potential in diagnosis, therapeutic intervention, and prognostic evaluation." (PMID 40381082, 2025). "The lysozyme in phagocytes may participate by various mechanisms in the reduction of inflammation and colorectal cancer in the absence of Nod2-mediated signaling." (PMID 37876927, 2023).
diabetes (8 papers, 2019 to 2025). "Antimicrobial proteins and tests of association: the salivary lysozyme was significantly lower (p=0.01) in the patients with diabetes measuring a median 32.5 ng/ml (IQR 25.0-39.6) compared to 36.4 ng/ml (IQR 31.4-42.1) in the non-diabetic control group." (PMID 36762154, 2022). "Studies previously showed that glycation alters conformation of lysozyme secondary and tertiary structures, and the loss of α-helix results in reduction in its bactericidal and enzymatic activity, thereby increasing susceptibility to bacterial infections in diabetes." (PMID 35061788, 2022). "Donkey milk exhibits particularly high lysozyme content and demonstrates significant immunomodulatory effects, while camel milk shows remarkable therapeutic potential in diabetes management, nephroprotection, and hepatoprotection." (PMID 40722905, 2025). "We also found that lysozyme and histatins are negatively correlated with plasma glucose level, and that patients with diabetes are more likely to have reduced levels of these antimicrobial proteins." (PMID 36762154, 2022). "Correlation analysis done showed that levels of salivary lysozyme (r = -0.127; p=0.163) and histatins (r = -0.025; p = 0.424) were both negatively correlated with plasma glucose levels in the patients with diabetes." (PMID 36762154, 2022). "On the contrary, a similar study done in paediatric patients with diabetes reported a significantly higher salivary lysozyme levels compared to the control group, although the total salivary protein was significantly lower." (PMID 36762154, 2022). "patients with diabetes had reduced levels of salivary lysozyme and histatins, this could provide an insight into the associated high oral infection rates." (PMID 36762154, 2022). "However, our study showed that salivary lysozyme level is significantly reduced in the patients with diabetes." (PMID 36762154, 2022). "In concrete, HSA may appear alongside or instead of lysozyme in some kinds of proteinurias, such as those induced by renal damage or diabetes." (PMID 33804443, 2021). "In this study, we found a reduced levels of lysozyme and histatins in the saliva of patients with diabetes compared to those of the healthy non-diabetic controls." (PMID 36762154, 2022). "The median salivary lysozyme was 32.5 ng/ml (IQR 25.0-39.6) in the group with diabetes and 36.4 ng/ml (IQR 31.4-42.1; p=0.01) in the non-diabetic control group." (PMID 36762154, 2022). "This study evaluated salivary lysozyme and histatins, two major innate antimicrobial proteins, in patients with diabetes and non-diabetic controls." (PMID 36762154, 2022). "Thus, the aim of this study is to compare the levels of salivary lysozyme and histatins which are major innate antimicrobial proteins between patients with type 2 diabetes mellitus and healthy non-diabetic controls." (PMID 36762154, 2022).
gingivitis (8 papers, 2008 to 2025). A disorder involving inflammation of the gums; may affect surrounding and supporting structures of the teeth. "The present study involved the use of a mouth rinse consisting of sea salt, the antimicrobial enzyme lysozyme, and xylitol, a polyalcohol commonly used as a nonsugar sweetener, to determine its effect on plaque biofilm and gingivitis in a group of dental students." (PMID 29619048, 2017).
Hypertension (8 papers, 2013 to 2025). The presence of chronic increased pressure in the systemic arterial system. "LYZ is a plasma biomarker of atherosclerosis, and LYZ is associated with vascular-related diseases, including hypertension, diabetic nephropathy, and abdominal aortic aneurysm, with significantly elevated LYZ expression in peripheral blood and other tissues." (PMID 40416362, 2025). "An early stage of cardiovascular problems, hypertension,has been linked to higher amounts of salivary lysozyme." (PMID 37693919, 2022). "With regard to lysozyme, earlier publications have reported the oral infections, hyperglycemia, hypertension, and metabolic syndrome significantly associated with increased salivary levels of lysozyme." (PMID 27294141, 2016). "Salivary lysozyme has been reported to be associated with hypertension, coronary artery disease, and arterial stiffness." (PMID 27294141, 2016). "In earlier publications, oral infections, hyperglycemia, hypertension and metabolic syndrome show a significant association with increased salivary levels of lysozyme." (PMID 23637817, 2013). "In two different studies, lysozyme in saliva was associated with hypertension." (PMID 33443617, 2021). "This review mainly introduced the antibacterial, antifungal, and antiviral mechanisms of lysozyme, as well as its application in diseases such as cancer and hypertension." (PMID 34925025, 2021). "Researchers have found that increased lysozyme content in the saliva is an indicator of the early stage of hypertension." (PMID 34925025, 2021). "Logistic regression analysis of 500 Finnish people with or without coronary heart disease in the Kuopio oral health and heart study showed that people with higher levels of lysozyme were more likely to suffer from hypertension." (PMID 34925025, 2021). "In conclusion, indirect and direct evidence shows that lysozyme is an index to predict hypertension and other related diseases by regulating inflammatory immune response." (PMID 34925025, 2021). "In our investigation, lysozyme concentration was higher in the saliva of patients reporting inflammatory conditions and/or high blood pressure." (PMID 23637817, 2013). "It is indirectly proved that the increase of lysozyme is an early index of hypertension." (PMID 34925025, 2021). "Several studies have already investigated a possible interplay between lysozyme and hypertension." (PMID 33443617, 2021). "Variable inflammation, which could include a combination of systemic conditions like heart disease, high blood pressure, bowel disease, and muscle and joint diseases, was associated with increased concentrations of IL-8, MMP-8, MMP-8/TIMP-1 ratio, lysozyme and total protein." (PMID 23637817, 2013). "Patients reporting high blood pressure presented with higher concentrations of MMP-8 and lysozyme, as well as an increased MMP-8/TIMP-1 ratio but these differences were lost after compensation for age, gender and smoking habits." (PMID 23637817, 2013). "It was found that the infiltration of monocytes- and macrophages-secreting lysozyme may be an important factor in ATII-induced vascular dysfunction and arterial hypertension." (PMID 34925025, 2021).
intestinal infection (8 papers, 2011 to 2026). "The results of other studies show that a lysozyme, together with lactoferrin and immunoglobulin, can inhibit the growth of gastrointestinal pathogenic microorganisms and reduce the incidence of gastrointestinal infection in infants." (PMID 38137269, 2023). "The cross-linker-free and pH-responsive CS/CMS-lysozyme microspheres can be a promising oral antibacterial additive for the treatment of intestinal infection." (PMID 36904318, 2023). "It is important to note that trx-3 mRNA induction upon P. luminescens infection is similar to that of the lysozyme lys-2, a well-known marker for intestinal infection in C. elegans." (PMID 24316195, 2014). "The genes induced by intestinal pathogen-infection included genes with known involvement in the response to intestinal infection, e.g. eight C-type lectins and the lysozyme lys-2." (PMID 21602919, 2011). "Lysozyme, lactoperoxidase and lactoferrin have been recognized as antimicrobial and bacteriostatic agents and could be useful to prevent intestine infections in infants." (PMID 28239105, 2013). "Immunocompromized patients, those recovering from gastrointestinal infections, or children with recurrent respiratory or enteric illnesses may particularly benefit from the antimicrobial and anti-inflammatory synergy of this protein-rich, lysozyme-dense milk matrix." (PMID 41464990, 2025). "We reveal many novel adaptive loci with convergent signals from selection, infectious disease GWAS and immune-gene QTLs (including at FUT6 for intestinal infections; at ASAP1 for TB; and at LYZ, an antimicrobial enzyme), fine-mapping selection onto likely causal variants." (PMID 42039401, 2026).
rheumatoid arthritis (8 papers, 2009 to 2025). A chronic, systemic autoimmune disorder characterized by inflammation in the synovial membranes and articular surfaces. "Immunohistochemical staining of rheumatoid nodules has shown positive staining of epithelioid cells for HLA-DR, CD68, lysozyme, MMP-2, MMP-3, MMP-9 and Ki67." (PMID 19604347, 2009). "By performing intersection analysis on 35 cervical cancer prognosis related genes and RA differential genes, a total of 3 co-upregulated differential genes were identified, namely SPP1, LYZ, and MCM5, which were upregulated in patients with rheumatoid arthritis and cervical cancer." (PMID 41384115, 2025). "As lysozyme hydrolyzes only the non-O-acetylated portions of the PG sacculus, large molecular weight (O-acetylated) fragments continue to circulate in the patient, a condition that leads to the development of e.g., pelvic inflammatory disease and rheumatoid arthritis." (PMID 31137799, 2019).
atherosclerosis (7 papers, 2017 to 2025). A disease characterized by the build-up of fatty material and calcium deposition in the arterial wall resulting in partial or complete occlusion of the arterial lumen. "For example, LYZ (Lysozyme) has been linked to vascular inflammation and the progression of atherosclerosis." (PMID 38474140, 2024). "LYZ has been involved in the development of atherosclerosis in a juvenile obesity pig model." (PMID 32214182, 2020). "Transgenic mice, which express the AA 15-lipoxygenating human ALOX15 under the control of the lysozyme promoter (macrophage specific expression) in addition to the endogenous AA 12-lipoxygenating mouse Alox15, are protected from arterial lipid deposition in a mouse atherosclerosis model." (PMID 40044044, 2025). "Our results verified that CAMP, LYZ, and PGLYRP1 were important factors in constituting the atherosclerosis of CHD." (PMID 34692829, 2021). "Blood transcriptomes revealed pyridoxal 5’phosphate salvage, pyrimidine ribonucleotides salvage pathways, atherosclerosis, and cell movement signaling with membrane CD9 and extracellular lysozyme as effectors." (PMID 28053879, 2017).
colon carcinoma (7 papers, 2016 to 2024). "Taken together, DKK2-driven loss of HNF4α1 protein enhances Sox9 expression in colon cancer cells to generate LYZ+ cells with Paneth cell properties." (PMID 38659853, 2024). "Notably, DKK2 induces the loss of HNF4α1 isoform in colon cancer cells followed by elevation of Sox9 expression lead to the formation of LYZ+ cancer cells exhibiting Paneth cell properties." (PMID 38659853, 2024). "DKK2 is required for the formation of LYZ+ colon cancer cells exhibiting Paneth cell properties such as glycolysis for stem cells." (PMID 38659853, 2024). "Single cell RNA sequencing analyses for mouse and human metastatic colon cancer samples have identified the existence of LYZ+ cells exhibiting Paneth cell properties including metabolic support for stem cells." (PMID 38659853, 2024). "Single cell RNA sequencing analyses of murine metastasized colon cancer cells and patient samples identified the presence of lysozyme positive cells with Paneth cell properties including enhanced glycolysis." (PMID 38659853, 2024). "To unravel the functional significance of LYZ+ cancer cells, we performed gene set enrichment analysis for the scRNA-seq data obtained from colon cancer patients." (PMID 38659853, 2024). "Single cell RNA-seq analyses for mouse and human metastatic colon cancers have identified the existence of LYZ+ cancer cells harboring Paneth cell properties, in particular, glycolysis for stem cells." (PMID 38659853, 2024). "Our findings suggest that DKK2 promotes LYZ+ cell formation exhibiting Paneth cell properties to develop cancer stem cell niches for outgrowth of metastasized colon cancers." (PMID 38659853, 2024). "Taken together, DKK2-mediated reduction of HNF4A protein promotes the generation of lysozyme positive cancer cells with Paneth cell properties in the metastasized colon cancers." (PMID 38659853, 2024). "Single-cell RNA sequencing (scRNA-seq) analyses for mouse and human metastatic colon cancer samples have identified the existence of LYZ+ cells exhibiting Paneth cell properties including metabolic support for stem cells." (PMID 39535280, 2024). "Our study suggests the presence of LYZ+ cells exhibiting Paneth cell properties in the context of colon cancer and metastasis." (PMID 38659853, 2024). "DKK2 expression in colon cancer promotes LYZ+ cancer cell generation through the regulation of HNF4α1, which suppresses expression of Sox9, the transcription factor for Paneth cell differentiation." (PMID 38659853, 2024). "Reduced staining for CGA+ neuroendocrine and lysozyme+ Paneth differentiated cells was found in colonic tumor tissue in comparison to normal colon." (PMID 35743243, 2022).
colon carcinoma (continued). "Several reports have shown the presence of similar lysozyme-positive cells in human colon cancer tissues; chemical-induced in vivo acute deletion of Apc genes in the mouse colon also resulted in the emergence of lysozyme-positive cells." (PMID 33597597, 2021). "This suggests a reduction of LYZ+ cells in metastasized colon tumors by knockout a Dkk2 gene." (PMID 38659853, 2024). "DKK2-deficient colon cancer cells possessed high levels of HNF4α1 protein and failed to generate LYZ+ cancer cells in vitro and in vivo." (PMID 38659853, 2024). "HNF4A mediates the formation of Lysozyme positive colon cancer cells by DKK2." (PMID 38659853, 2024). "To unravel the functional significance of LYZ+ cancer cells, we performed gene set enrichment analysis (GSEA) for the scRNA-seq data obtained from colon cancer patients." (PMID 39535280, 2024). "Using a novel human colonic biopsy model and polarized T84 colon carcinoma cells, we found that EHEC infection induced expression of human β-defensin 2 (hBD2), whereas hBD1, hBD3, LL-37, and lysozyme remained unchanged." (PMID 27446815, 2016). "Notably, neither lysozyme nor CGA staining was observed in the neoplastic epithelium in colonic tumor tissue, but staining was observed within the stroma." (PMID 35743243, 2022). "Moreover, we found a significant number of lysozyme-positive Paneth-like cells, which were never observed in wild-type colon tissues or organoids, but have been reported to emerge in colon cancers." (PMID 33597597, 2021). "However, it has been reported that such lysozyme-positive cells ectopically emerge in human colon cancer tissues and in mouse colon lacking Apc genes." (PMID 33597597, 2021).
cystic fibrosis (7 papers, 2012 to 2021). Autosomal recessive disorder caused by pathogenic variants in the CFTR gene (cystic fibrosis transmembrane conductance regulator), which encodes a chloride and bicarbonate channel expressed in epithelial cells, and follow the diagnosis criteria. "Although lysozyme has been proposed to play a crucial role in host defense, persistent P. aeruginosa airway infection is a major cause of morbidity and mortality in cystic fibrosis patients." (PMID 28299285, 2017). "A fusion protein, composed of lysozyme and surfactant protein B, was proposed for the prophylaxis or the therapeutic strategy for suppressing the bacterial colonization of the airways in cystic fibrosis patients." (PMID 34943746, 2021). "Strains isolated from patients with cystic fibrosis, chronic infection, acute infection and environmental strains also showed reduced metabolic activity after incubation with 20 or 80 μM lysozyme (p < 0.0001)." (PMID 32443413, 2020).